SPHK1 (sphingosine kinase 1)
Diseases named in the same sentence as SPHK1 in open-access papers (continued):
Sharing a sentence is not in itself a finding about the gene and the disease.
Sepsis (continued). "We therefore tested the influence of altered systemic S1P levels in circulation on VEC barrier stability and sepsis severity by inducing a systemic polymicrobial infection to wt, SphK1−/− and SphK2−/− mice." (PMID 36361636, 2022). "In order to investigate the role of SphK1 and SphK2 in sepsis, we used the experimental sepsis model of polymicrobial peritoneal contamination and infection (PCI) in mice." (PMID 36361636, 2022). "Decreased S1P levels in human sepsis is likely the result of reduced sphingosine kinase (Sphk1 and Sphk2) activity." (PMID 34087197, 2021). "In the present study, we aimed to explore the effect of SphK1 inhibition on HMGB1 translocation and the underlying mechanism during sepsis-associated liver injury." (PMID 33281190, 2020). "Previous studies have reported that SphK1 and HMGB1 are activated in sepsis-associated liver injury." (PMID 33281190, 2020). "In this study, we aimed to investigate the effect of SphK1 inhibition on HMGB1 translocation and the underlying mechanism of sepsis-associated liver injury." (PMID 33281190, 2020). "Surface C5aR2 on neutrophils and peritoneal macrophages maintained by sphingosine kinase 1-sphingosine-1-phosphate (Sphk1-S1P) interaction dampened inflammation in endotoxin-induced sepsis in mice, in part through ERK1/2." (PMID 28706957, 2017). "Studies have also shown that abnormal changes in SphK1 or S1P lead to many inflammatory and autoimmune diseases, including asthma, rheumatoid arthritis, sepsis, inflammatory bowel disease and so on." (PMID 27994962, 2016). "Pro-inflammatory cytokines and GCs, via GR, induce sphingosine kinase 1 (Sphk1) in a model of acute lung injury (ALI)—a complication of sepsis." (PMID 28018358, 2016). "Thrombocyte-derived microvesicles trigger the upregulation of SPHK1 in monocytic cells in inflammation and sepsis." (PMID 26607226, 2015). "Pharmacological inhibition of Sphk1 enzymatic activity has been reported as beneficial in mouse sepsis models." (PMID 22355325, 2012). "LPS activates Sphk1 and Sphk1 protein expression is up-regulated in macrophages and neutrophils from patients with severe sepsis." (PMID 22355325, 2012). "Previous results point to increased Sphk1 protein expression as required to promote inflammation in sepsis or as a compensatory mechanism to curb inflammation." (PMID 22355325, 2012). "In comparison, SPHK1 was involved in sepsis-induced inflammation." (PMID 38791593, 2024). "Interestingly, several reports suggested that SPHK1 inhibition showed a clear potential therapeutic advantage against sepsis." (PMID 36653338, 2023). "The fact that both SphK1−/− mice and SphK2−/− mice were characterized by increased survival rate upon sepsis induction made us wonder whether the VEC barrier was influenced by different S1P levels in plasma of the respective mice or not." (PMID 36361636, 2022). "Previous studies have confirmed that CD47, Lcn2, and Sphk1 were involved in the sepsis process." (PMID 33204219, 2020). "However, little information is available on the association between SphK1 and HMGB1 translocation during sepsis-associated liver injury." (PMID 33281190, 2020). "This paved the way for the exploration of SphK1 inhibitors for the treatment of sepsis in humans." (PMID 27129720, 2016). "Therefore, deletion or inhibition of SphK1 prevented sepsis in mouse models of LPS challenge or cecal ligation and puncture." (PMID 27129720, 2016). "It has also been reported that Sphk-1 is upregulated in stimulated human phagocytes and peritoneal phagocytes of patients with severe sepsis and potentially plays a role in the development of sepsis." (PMID 23817990, 2013). "It remains unclear how increased expression of the Sphk1 protein or increased Sphk activity in patients' phagocytes correlates with or determines sepsis outcome or lung inflammation." (PMID 22355325, 2012). "Thus, Sphk1 is required for the S1P gradient between lung plasma and tissue in LPS-induced experimental sepsis." (PMID 22355325, 2012).
Sepsis (continued). "We therefore suggest that reduced IFN-γ release by SphK1/2 deficient DC dampen the early inflammatory response and cytokine release of macrophages, which, in turn, may have led to the observed increased survival of SphK1−/− and SphK2−/− mice in experimental sepsis." (PMID 36361636, 2022). "Surprisingly, both, SphK1−/− and SphK2−/− mice demonstrated alleviated disease progression compared to wild-type (wt) mice despite their opposite modulation of S1P levels in circulation, suggesting that altered systemic S1P levels have little effect on sepsis outcomes." (PMID 36361636, 2022). "It was also involved in sepsis-associated liver injury via induction of the intracellular translocation of the high-mobility group box 1 (HMGB1), which, in turn, was associated with a direct interaction of SphK1 and the calcium/calmodulin protein kinase II-δ (CaMKII-δ)." (PMID 36361636, 2022). "The inhibition of SphK1 expression could suppress neutrophil activation and decrease lung permeability and cytokine formation, and its protective effects had been elaborated in allergic asthma and sepsis-induced inflammation." (PMID 29249870, 2017). "Moreover, SPHK-1 can be activated by and regulates signaling through C5a receptors, which also play central roles in the initiation and progression of inflammation in sepsis." (PMID 26607226, 2015). "Thus, it appears that Sphk-1 may play a significant role in sepsis in the elderly by increasing the expression of proinflammatory cytokines." (PMID 23817990, 2013). "Moreover, the deletion of Sphk1 in mice reduced significantly the lethality in LPS-induced sepsis." (PMID 22355325, 2012). "Besides the disease models addressed in this study, increased levels of S1P were found in the blood of diabetic patients and upregulated sphingosine kinase 1 (SK1) has been detected in phagocytes of patients with sepsis where it promotes excessive production of pro-inflammatory cytokines." (PMID 21829623, 2011). "Here, we investigated the role of SphK1 and SphK2 in polymicrobial peritoneal contamination and infection (PCI) as an experimental sepsis model in mice." (PMID 36361636, 2022). "In sepsis, both TLR2 and TLR4 stimulated and upregulated SphK1 and downstream factors such as NF-κB." (PMID 27129720, 2016). "For example, low concentration of S1P promotes inflammatory cell chemotaxis, whereas high concentration is inhibitory Etiologic agents and mediators of sepsis, including LPS, TNF-α, and complement anaphylatoxin C5a activate Sphk1 in PMNs and macrophages." (PMID 22355325, 2012). "Moreover, in macrophages, S1P is catalyzed by SphK1 and binds to S1PR3 to regulate aerobic glycolysis and influence macrophage polarization, mediating the inflammatory response in sepsis." (PMID 39935473, 2025). "In other inflammatory diseases such as sepsis, plasma or serum S1P levels are known to severely drop in humans, WT mice, and SphK1−/− mice, but not in SphK2−/− mice." (PMID 39062926, 2024). "Studies have shown that SphK1 is 15 times higher than SphK2 in normal human body, while the expression of SphK1 in platelets of sepsis patients is significantly reduced, while SphK2 has no significant change." (PMID 37746079, 2023). "Performances of each single marker (leukocytes, thrombocytes, C5, HP, SPHK1, and the routinely used laboratory parameters CRP and PCT) were compared with respect to various outcomes (sepsis, nosocomial infections, mortality) and time points of assessment (day 0, day 1, all days)." (PMID 26607226, 2015). "Sphk1 is a pro-inflammatory factor, and inhibition of Sphk1 can inhibit the activation of NLRP3 inflammasome and the release of IL-1β in macrophages and improve the survival rate and pulmonary vascular leakage of cecal ligation and puncture (CLP)-induced sepsis mice." (PMID 38482014, 2024).
Sepsis (continued). "By regulating the expression of Sphk1 and S1P, kaempferol can inhibit the NF-kb pathway, reduce the expression of the inflammatory mediators NO and PGE2, alleviate the inflammatory response of LPS-induced sepsis, and stabilize the pulmonary vascular endothelial barrier." (PMID 38482014, 2024). "Dusp, SphK1, IL10, ATF4, VEGF, CEBP, PGC1a, and PPARg were not significantly affected by sepsis (data not shown)." (PMID 32477273, 2020).
colitis (27 papers, 2013 to 2025). Inflammation of the colon. "A recent study has reported that SPHK1 leads to the constitutive activation of STAT3 in colitis-associated CRC." (PMID 30555277, 2018). "Consistent with earlier findings, the colitis group exhibited markedly elevated levels of S1P and SPHK1 compared to healthy controls." (PMID 40387460, 2025). "In the current model, both PTX and mesalamine significantly reduced colonic levels of S1P and SPHK1 compared to the untreated colitis group." (PMID 40387460, 2025). "The SphK1 inhibitor PF-543 had an inhibitory effect in a DSS-induced colitis mouse model, indicating that the SphK-S1P axis is closely associated with the progression of IBD." (PMID 37560160, 2023). "Previous studies have shown that elevated SphK1-S1P in a DSS-induced colitis mouse model led to increased neutrophilia in circulation and increased neutrophil infiltration in the colon." (PMID 37560160, 2023). "Of interest, phosphorylated-FTY720 was shown to inhibit colitis-associated CRC growth and proliferation by suppressing SphK1 and S1P1 receptor expression." (PMID 34768523, 2021). "SPHK1 is upregulated in CRC cancer patients and leads to constituent activation of STAT3 in colitis-associated CRC." (PMID 30555277, 2018). "Other studies using different models, namely, tumour cells, acute colitis and knock out mice in which Sphk2 expression was depleted, showed an increase of Sphk1 expression, activity and S1P levels." (PMID 28753653, 2017). "Sphk-1 expression has been found to increase in IBD and in a mouse model of colitis and Sphk-1 gene deficiency markedly decreased the systemic inflammatory response." (PMID 23817990, 2013). "SphK1 is overexpressed in colon of IBD patients and in mice with DSS-induced colitis, and mice lacking SphK1 are less susceptible to experimentally induced IBD." (PMID 28300788, 2017). "To investigate whether PCA ameliorates colonic damage in mice with TNBS-induced colitis through the regulation of the SphK/S1P axis, we first examined the expression of SphK1 by qRT-PCR, Western blot and immunohistochemistry." (PMID 28300788, 2017). "For example, the SphK1-S1P-S1PR1 axis has a significant role in IBD, with increased S1P levels and elevated SphK1 expression observed during colitis." (PMID 40063366, 2025). "The severity of colitis is increased by elevated COX-2 levels in Sphk2–/– mice, and Sphk2 depletion enhances Sphk1 expression." (PMID 38482014, 2024). "By upregulating the Sphk1/S1P/S1PR1 axis and activating the NF-κB and STAT3 pathways in acute colitis, experimental data suggest that Sphk2 exerts anti-inflammatory effects." (PMID 38482014, 2024). "This was further confirmed by performing animal experiments using PF-543 (a SphK1 inhibitor), which inhibits DSS-induced colitis, and gut-specific knockout of S1PL, which leads to increased S1P levels in the colon and aggravates IBD symptoms." (PMID 37560160, 2023). "Previously, our group discussed the role of SphK1 and S1P in dextran sulfate sodium (DSS)-induced colitis, AOM-induced aberrant crypt foci (ACF, colonic preneoplastic lesion) and AOM/DSS-induced inflammation-related colon carcinogenesis." (PMID 28583134, 2017). "Several experimental studies have investigated the therapeutic potential of PTX in models of colitis; however, the present study is the first to elucidate its modulatory effects on the SPHK1/S1P, IL‐6/STAT3, AMPK/mTOR/NLRP3, and ZO‐1 signaling pathways in experimental colitis." (PMID 40387460, 2025). "Similar to Sphk1, S1PR1 is also upregulated in AOM/DSS-induced murine models of colitis and CAC." (PMID 28991193, 2017). "Although the absence of SphK1 was protective against DSS-induced colitis, SphK2 depletion resulted in enhanced proliferation and proinflammatory cytokine production, and thus IBD progression." (PMID 26880864, 2016).
colitis (continued). "Hence, the findings of this study support the hypothesis that PTX attenuates SPHK1/S1P signaling via inhibition of TNF‐α and activation of the cAMP/PKA axis, contributing to its anti‐inflammatory effects in colitis." (PMID 40387460, 2025). "Another difficulty with the Alvarez interpretation of their data is that Sphk1-/- mice are viable and relatively normal, while Traf2 knock-outs on a C57BL/6 background die before or shortly after birth and on a BALB/c background develop severe colitis and die within three weeks after birth." (PMID 26701909, 2015).
diabetes (25 papers, 2014 to 2025). "We have recently reported that global deletion of either Sphk1 or Sphk2 exhibited a significant impact on diabetes in the animal models, i.e., loss of Sphk1 promotes, but Sphk2 deficiency protects, the disease." (PMID 34530846, 2021). "Feeding sphingosine kinase 1 gene-deficient and wild-type mice a high-fat diet results in sphingosine kinase 1 gene-deficient mice suffering from diabetes, while wild-type mice only show mildly impaired blood glucose regulation." (PMID 34751249, 2021). "Several pathological conditions including cancer, diabetes, inflammatory, and neurodegenerative diseases have been linked to defective homeostatic levels of SphK1/S1P." (PMID 32526899, 2020). "In DKD, recent studies have demonstrated that mice with podocyte-specific deletion of S1P lyase develop proteinuria, and increased glomerular S1P resulting from increased SPHK1 activity is associated with increased mesangial proliferation in STZ-induced diabetes." (PMID 38200266, 2024). "For instance, we have recently reported that global deletion of Sphk1 in mice resulted in a significant loss of pancreatic β-cell mass and promoted the onset of diabetes, whereas Sphk2 deficiency ameliorated diabetic phenotype by protecting β-cells against lipoapoptosis." (PMID 34530846, 2021). "Indeed, induction of diabetes by an injection of streptozotocin leads to the activation of SphK1 associated to an inflammatory phenotype in vascular endothelium and retina." (PMID 26237395, 2014). "In addition, complications associated with the use of SphK1/S1P inhibitors may be that cancer patients are more susceptible to diabetes development." (PMID 25866760, 2015). "SIP, a potential biomarker in many diseases, including diabetes, is synthesized from sphingosine by two sphingosine kinases: SPHK1 and SPHK2." (PMID 41301404, 2025). "The expression and activity of SphK1 were increased in diabetic kidney, MCs, RTCs and VSMC, while SphK2 remained unchanged in diabetic kidney, MCs and VSMC." (PMID 35409370, 2022). "So far, only hepatocyte-specific Sphk2-/- and adipocyte-specific Sphk1-/- have been applied in diabetes research." (PMID 33633691, 2020). "Taken together, our findings that SphK1 protects but SphK2 promotes β-cell lipotoxicity suggest a new strategy by balancing between the signaling of SphK1 and SphK2 in β-cells for the prevention and treatment of diabetes." (PMID 33633691, 2020). "Recently, SphK1 has received a great attention due to its involvement in a number of human pathologies, including cancer, rheumatoid arthritis, pulmonary fibrosis, diabetes, asthma and neurodegenerative disorders." (PMID 31822735, 2019). "In fact, upregulation of SphK1 and its effector molecule S1P has been well established in various cancers and other human pathologies like pulmonary fibrosis, diabetes and Alzheimer’s disease." (PMID 31822735, 2019). "SphK1 is activated under stimulation of advanced glycation end products (AGEs) or oxidative stress during the period of diabetes, accompanied by formation of S1P to mediate the biological and physiological activities of cells." (PMID 29179493, 2017). "AP-1, a dimer mainly formed by proteins of the Fos and Jun, is activated under HG stimulation and directly binds with its binding sites in SphK1 promoter to trigger SphK1 gene transcription, forming a positive feedback loop in diabetes." (PMID 29179493, 2017). "The SphK1 isoenzyme is expressed in most tissues, and its role as a major player in development and disease has been widely researched over the past 20 years, including its role in cancers, diabetes, and liver pathology." (PMID 36532885, 2022). "Diabetes increased the production of S1P by increasing the expression of the SphK1 gene." (PMID 35414826, 2022). "SphK1(−/−) mice developed diabetes and had reduced insulin levels compared with the WT mice." (PMID 34943862, 2021).
diabetes (continued). "In white adipose tissue, SphK1 prevents obesity-associated diabetes, whereas the adipose-specific role of SphK2 is not known." (PMID 34943862, 2021). "SphK1/S1P inhibitors as therapies for diabetes are also problematic." (PMID 25866760, 2015). "However, increased staining of SphK1 was observed in the diabetes mouse kidney." (PMID 29108256, 2017). "Inhibitors of SphK1 are currently being explored for cancer treatment; however, with the high probability of comorbidity of cancer and diabetes, the possibility of cancer treatments such as SphK1 inhibitors promoting insulin resistance may have dire consequences for cancer survivors." (PMID 25866760, 2015). "A greater understanding of the actions of SphK1/S1P in the context of diabetes, especially the onset of type 2 diabetes and cancer, is required if we are to switch the sphingolipid rheostat in the treatment of diabetes and cancer comorbidity from a problem to an advantage." (PMID 25866760, 2015). "Despite increased sphingoid-1-phosphate levels in diabetic pregnancies with preeclampsia, no changes were seen in placental SPHK1 or SPHK2 enzyme levels in either diabetes type in the presence of preeclampsia." (PMID 36979912, 2023).